LSINCT5 (long stress-induced non-coding transcript 5)
Gene: Long non-coding RNA gene on chromosome 5 (2,712,591 to 2,715,237, forward strand). Ensembl gene ENSG00000281560.
Diseases named in the same sentence as LSINCT5 in open-access papers:
LSINCT5 is named in the same sentence as 14 diseases in open-access papers, as found by Europe PMC text mining. Sharing a sentence is not in itself a finding about the gene and the disease. The quoted sentences say what the papers report.
ovarian carcinoma (8 papers, 2014 to 2019). A malignant neoplasm originating from the surface ovarian epithelium. "LSINCT5 is overexpressed in ovarian cancer cell lines and tumor tissues and implicated in the cellular proliferation and development of ovarian cancer." (PMID 28154416, 2017). "Several dysregulated lncRNAs, such as HOTAIR and LSINCT5, are associated with ovarian cancer survival." (PMID 28154416, 2017). "Furthermore, it was suggested that loss of LSINCT5 function inhibited proliferation in breast and ovarian cancer cell lines." (PMID 29921308, 2018). "Silva and co-workers first found LSINCT5 was over-expressed in breast and ovarian cancer cell lines and tumor tissues, relative to their normal counterpart." (PMID 29921308, 2018). "Many breast and ovarian cancer cell lines as well as tumor sample panels have been reported to overexpress LSINCT5." (PMID 28637507, 2017). "Knockdown of LSINCT5 significantly impaired the proliferation of both breast and ovarian cancer cells." (PMID 27535740, 2016). "LSINCT5 has been shown to be overexpressed in many breast and ovarian cancer cell lines and tumor samples." (PMID 26992233, 2016). "This is supported by LSINCT5 knockdown in breast and ovarian cancer cell lines, which impairs proliferation." (PMID 25400658, 2014). "LSINCT5, the stress-regulated lncRNA, is overexpressed in breast and ovarian cancer cell lines and tumor tissues." (PMID 25288503, 2014). "Although these studies provide only limited data regarding ovarian carcinomas, they suggest that LSINCT5 might play a role in these cancers." (PMID 26992233, 2016). "Expression of LSINCT5 is increased in several cancers, including breast and ovarian cancer." (PMID 25400658, 2014). "In addition, LSINCT5 has been proved to play a role in cellular proliferation and also in the development of breast and ovarian cancers." (PMID 25288503, 2014). "LSINCT5 is considered as a stress-regulated lncRNA and a novel nuclear-expressed gene that might have an important role in cellular proliferation in the development of breast and ovarian cancer." (PMID 28637507, 2017).
breast carcinoma (4 papers, 2019 to 2022). "For example, the expression of LSINCT5 in primary breast cancer tissues is ten times higher than that in normal tissues, which enhances the invasion of breast cancer cells via chemokine receptor (CXCR4)." (PMID 34057025, 2021). "For example, LSINCT5 and Zfas one can promote the proliferation of breast cancer, HOTAIR suppresses invasion and migration of breast cancer, SOX2OT induces SOX2 expression in breast cancer, and SRA is the expression activator of breast cancer." (PMID 36744179, 2022).
gastric cancer (4 papers, 2016 to 2020). A primary or metastatic malignant neoplasm involving the stomach. "Recently, LSINCT5 overexpression has been identified in lung cancer, hepatocellular carcinoma, bladder cancer, gastric cancer and colorectal cancer." (PMID 30967495, 2019).
bladder cancer (3 papers, 2019 to 2021). "Long stress-induced non-coding transcript 5 (LSINCT5) directly interacts with NCYM, and inhibits GSK3β activity, leading to Wnt/β-catenin signaling activation and promoting EMT in bladder cancer cell lines." (PMID 34422802, 2021).
osteosarcoma (3 papers, 2019 to 2024). A usually aggressive malignant bone-forming mesenchymal neoplasm, predominantly affecting adolescents and young adults. "In our results, we found LSINCT5 expression was increased in osteosarcoma tissue samples and cell lines, and high LSINCT5 expression was associated with advanced Enneking stage, large tumor size, high histological grade and present distant metastasis." (PMID 30967495, 2019). "Moreover, gain-of-function and loss-of-function studies suggested LSINCT5 functioned as oncogenic lncRNA to regulate osteosarcoma cell proliferation, migration and invasion." (PMID 30967495, 2019). "Similarly, the results of survival analysis also showed high LSINCT5 expression was associated with short overall survival in osteosarcoma patients." (PMID 30967495, 2019). "The overexpression of LSINCT5 can promote the proliferation, migration, and invasion of osteosarcoma cells in vitro, while the inhibition of its expression has the opposite effect." (PMID 39015175, 2024). "The expression levels of long stress-induced noncoding transcript 5 (LSINCT5) were upregulated in osteosarcoma tissues and cell lines." (PMID 34130697, 2021). "In our study, we also found LSINCT5 expression was increased in osteosarcoma tissues and cells, and obviously correlated with large tumor size, advanced clinical stage and poor prognosis." (PMID 30967495, 2019). "LSINCT5 has been suggested to function as oncogenic lncRNA to affect tumor behavior in several human cancers including osteosarcoma." (PMID 30967495, 2019). "Our study presented more evidence about the clinical significance and biological function of LSINCT5 in osteosarcoma." (PMID 30967495, 2019). "We found LSINCT5 expression was markedly increased in osteosarcoma tissues compared with adjacent normal tissues." (PMID 30967495, 2019). "LSINCT5 functions as oncogenic lncRNA to modulate osteosarcoma cell proliferation, migration and invasion." (PMID 30967495, 2019). "Osteosarcoma patients with high levels of LSINCT5 expression showed worse overall survival time than those with low levels of LSINCT5 expression." (PMID 30967495, 2019). "To identify LSINCT5 expression in osteosarcoma, we performed RT-PCR to detect LSINCT5 expression levels in osteosarcoma tissues and cell lines (HOS, G-292 and Saos-2), adjacent normal tissues and normal osteoblast cell line (hFOB1.19)." (PMID 30967495, 2019). "In general, LSINCT5 plays a carcinogenic role in osteosarcoma cells and may be a predictor of the clinical outcomes of osteosarcoma patients, and a promising candidate for osteosarcoma prognosis and treatment." (PMID 39015175, 2024). "Besides, osteosarcoma patients with high expression of LSINCT5 showed a trend toward decreased overall survival." (PMID 34130697, 2021). "To gain insight into the biological functional of LSINCT5 on osteosarcoma cells, we observed the LSINCT5 expression levels in osteosarcoma tissues and cell lines (HOS, G-292 and Saos-2), and chose G-292 cells for loss-of-function study and HOS cells for gain-of-function study." (PMID 30967495, 2019). "In our study, we further explored the clinical value of LSINCT5 expression in 124 osteosarcoma cases, and also observed that high LSINCT5 expression had significant correlations with advanced Enneking stage, large tumor size, high histological grade and present distant metastasis." (PMID 30967495, 2019). "In conclusion, our study suggests that LSINCT5 exerts oncogenic function in osteosarcoma cells, and may be a potential predictor for clinical outcome in osteosarcoma patients." (PMID 30967495, 2019). "Meanwhile, osteosarcoma cell lines (HOS, G-292 and Saos-2) also showed higher levels of LSINCT5 expression than normal osteoblast cell line (hFOB1.19)." (PMID 30967495, 2019). "Although the role of LSINCT5 in osteosarcoma was reported not long ago, the sample size of that study was limited." (PMID 30967495, 2019).
osteosarcoma (continued). "Interestingly, LSINCT5 was reported to be overexpressed in osteosarcoma tissues and cells, and inhibition of LSINCT5 significantly depressed osteosarcoma cell proliferation, migration and invasion not long ago." (PMID 30967495, 2019).
glioma (2 papers, 2021). A benign or malignant brain and spinal cord tumor that arises from glial cells (astrocytes, oligodendrocytes, ependymal cells). "Knockdown of lncRNA LSINCT5 in human glioma cells triggered cell apoptosis and suppressed cell viability, migration, and invasion." (PMID 34771549, 2021). "LncRNA NFAT5 and LSINCT5 are up‐regulated in glioma and promote the proliferation of glioma." (PMID 33336871, 2021).
hepatocellular carcinoma (2 papers, 2019 to 2020). A malignant tumor that arises from hepatocytes. "In hepatocellular carcinoma, lncRNA LSINCT5 acted as a competing endogenous RNA and sponged miR-4516 in regulated HMGA2 expression." (PMID 32549762, 2020).
myocardial ischemia (1 paper, 2021). A disorder of cardiac function caused by insufficient blood flow to the muscle tissue of the heart. "In conclusion, this study demonstrated that lncRNA LSINCT5 is upregulated during myocardial ischemia/reperfusion injury." (PMID 34184201, 2021).
cancer (7 papers, 2014 to 2025). A tumor composed of atypical neoplastic, often pleomorphic cells that invade other tissues. "The abnormal expression of LSINCT5 is usually associated with cancer progression and poor prognosis, and high LSINCT5 expression is associated with advanced Enneking stage, large tumor volume, high histological grade, and current distant metastasis." (PMID 39015175, 2024). "Numerous studies have shown that LSINCT5 could be implicated in cancer development and has critical roles in metastasis, proliferation, and apoptosis of cancerous cells." (PMID 34771549, 2021). "lncRNA long stress-induced non-coding transcript 5 (LSINCT5), an oncogenic RNA found to be associated with cancer growth and progression, is found to be overexpressed in EC." (PMID 40863727, 2025). "LSINCT5 has greater than ten-fold increased expression in all cancer cell lines tested as compared to normal cell lines from the same tissues." (PMID 36406273, 2022). "Bladder cancer, osteosarcoma, endometrial carcinoma, gastrointestinal cancer, and breast and ovarian cancers are among the cancers in which LSINCT5 plays significant roles in their progression." (PMID 34771549, 2021). "In recent years, dysregulated expression of LSINCT5 has been found in various human tumors, and was generally related to cancer progression and unfavorable prognosis." (PMID 30967495, 2019). "The dysregulated expression of LSINCT5 (long stress-induced non-coding transcript 5) has been found in various human tumors, and was generally related to cancer progression and unfavorable prognosis." (PMID 30967495, 2019). "Targeted knockout of lncRNA LSINCT5 significantly inhibited the proliferation of cancer cells." (PMID 36406273, 2022). "Because of its high expression in proliferative tissues and cancer, LSINCT5 could potentially function as a regulator of proliferation." (PMID 25400658, 2014). "Furthermore, the upregulation of the lncRNAs long stress-induced non-coding transcript 5 (LSINCT5), colon cancer-associated transcript 2 (CCAT2), competing endogenous lncRNA 2 (CERNA2), PVT1, and urothelial cancer-associated 1 (UCA1) have also been implicated in cancer-promoting mechanisms of OC." (PMID 34404407, 2021).
LSINCT5 also shares sentences with these, for which no sentence is quoted: tumor (3 papers); acute myocardial infarction (1); colorectal cancer (1); lung carcinoma (1); lymph node metastasis (1).